LEP (leptin)
Diseases named in the same sentence as LEP in open-access papers (continued):
Sharing a sentence is not in itself a finding about the gene and the disease.
cancer (continued). "As noted in previous studies from our and other laboratories, leptin and ObR tend to be coexpressed in different cancers." (PMID 18945363, 2008). "In these cancer cell lines, adipocytokine leptin stimulates cell growth, proliferation and invasion of the cells in vitro." (PMID 21566743, 2008). "Leptin and adiponectin act on cancer cells directly or indirectly by its receptors and downstream signaling pathways." (PMID 21566743, 2008). "Leptin has been reported to inhibit apoptosis in human colon and prostate cancer cell lines and in leukemic cells." (PMID 18162139, 2007). "Another metabolic action of leptin that has been reported is inhibition of apoptosis in human colon and prostate cancer cell lines and in leukemic cells." (PMID 18162139, 2007). "Several studies have shown the relationship between LEP and LEPR gene polymorphisms and human cancer." (PMID 16504019, 2006). "Over the feeding period, the area under the curve for glucose, cortisol and interleukin-6 were greater in the cancer group compared with the control group (P<0.05), whereas leptin was significantly less for the cancer group (P<0.05)." (PMID 15026790, 2004). "The clinical consequences of lower circulating concentrations of leptin and the greater concentrations of glucose, cortisol and interleukin-6 in cancer patients in the fed state are likely to be profound." (PMID 15026790, 2004). "In studies of cachectic cancer patients, the role of leptin appears more complex since the fall in leptin concentrations which accompanies a loss of body fat appears not to be associated with an improvement in energy balance." (PMID 15026790, 2004). "The molar ratio (molecular weights of leptin and interleukin-6 are 16 and 26 kDa, respectively) of the areas under the curve for leptin and interleukin-6 was approximately 1000-fold greater in the weight-losing cancer group (P<0.01)." (PMID 15026790, 2004). "Such an intervention would allow critical examination of the inter-relationships between circulating concentrations of leptin, interleukin-6 and fat oxidation during feeding in healthy subjects and weight-losing cancer patients." (PMID 15026790, 2004). "Over a 4 h feeding period, the areas under the curve for glucose, cortisol and interleukin-6 were greater (P<0.05), but less for leptin in the cancer group (P<0.05)." (PMID 15026790, 2004). "At baseline, compared with the healthy subjects, cancer patients had less weight and fat mass (P<0.05) and had lower circulating concentrations of leptin (P<0.05), but higher concentrations of cortisol and interleukin-6 (P<0.05)." (PMID 15026790, 2004). "In the present study, at baseline, weight-losing cancer patients had less fat, lower leptin concentrations and had increased concentrations of the catabolic mediators cortisol and interleukin-6." (PMID 15026790, 2004). "Several proteins positively associated with MVPA are inversely associated with disease risk (e.g., integrins, CLEC4A for cancer; LPL, LEP for T2D), while proteins negatively associated with MVPA are positively associated with disease risk (e.g., CD38, TGFA for CVD)." (PMID 41826625, 2026). "Leptin is synthesized by adipocytes in response to overall fat mass and is also released from other sources such as the stomach, skeletal muscle, placenta, and cancer cells." (PMID 41562922, 2026). "A recent review suggested recruitment of ASCs from ppWAT into PCa cells and the TME are precursors to tumor stromal cells and cancer‐associated fibroblasts and a source of IL‐6, TNFα, CXCL1, CXCL5, CXCL8, CXCL12, MCP‐1, and leptin facilitating tumor angiogenesis and cancer cell proliferation." (PMID 41450167, 2026). "Therefore, while the determination of leptin hormone plays an important role in obesity diagnosis (or monitoring), it can also be seen as a potential biomarker in the diagnosis of certain cancer types." (PMID 39789177, 2025).
cancer (continued). "Furthermore, Leptin appears to influence the cancer immune response by inducing a pro-inflammatory immune polarization." (PMID 41409302, 2025). "These metabolic effects suggest a potential connection between leptin dysregulation and cancer." (PMID 40387523, 2025). "Leptin displays varied behavior in cancer cachexia across different cancer types." (PMID 40869331, 2025). "Particularly, leptin is identified as a marker for colorectal cancer-derived cancers, and in some conditions, it may have a carcinogenic role." (PMID 39789177, 2025). "However, its influence extends beyond metabolic functions, as research increasingly links leptin to cancer progression." (PMID 40387523, 2025). "This paradox highlights the complicated role of leptin in cancer therapy." (PMID 40863244, 2025). "Additionally, adipokines such as adiponectin and leptin play key roles in modulating cellular proliferation, angiogenesis, and metastasis in both cancer types." (PMID 41189943, 2025). "SHBG and leptin, when interpreted in context, provide mechanistically grounded biomarkers that support timely metabolic intervention before the onset of pathology such as cancer progression." (PMID 41586225, 2025). "Furthermore, leptin has been shown to impact cancer cell metabolism significantly and mitochondrial dynamics." (PMID 40485730, 2025). "Moreover, leptin downregulates Treg cell differentiation, leading to a poor prognosis in different types of cancers." (PMID 40227577, 2025). "In the context of cancer, many of the physiological signals sensed by hypothalamic neurons are frequently altered; these include inflammatory cytokines/chemokines, including interleukin (IL-6), glucose, and endocrine hormones, such as leptin and ghrelin." (PMID 40740866, 2025). "In addition to leptin, leptin-R expression has been determined in diversified cancer types, including RCC." (PMID 41010935, 2025). "Third, adipokines such as leptin (which have proinflammatory effects) secreted by adipose tissue may promote cancer development." (PMID 40521210, 2025). "In cancer, LEP is considered to act as both a mitogenic and migration factor in malignant cells." (PMID 41221514, 2025). "We found an association between cancer and lower serum concentrations of PDGF-AB/BB and leptin." (PMID 40940878, 2025). "The main findings from this observational analysis are significant associations between aerobic physical activity (as measured by MVPA or steps), device-based tracking during six months after surgery, and VO2max, cardiac output, and metabolic biomarkers (insulin and leptin) in cancer survivors." (PMID 40783771, 2025). "Furthermore, adipokines such as leptin can induce the secretion of various MMPs by cancer cells as well as the angiogenic differentiation of endothelial cells, thereby indirectly promoting neovascularization and tumor progression." (PMID 39496581, 2025). "Increased ghrelin sensitivity, decreased leptin concentrations, elevated levels of IL-6 and blood glucose, and hyperactivity of HO neurons (increased cFos immunoreactivity) were observed in cancer mouse models during the development of sleep debris in the late phase of tumor growth." (PMID 40740866, 2025). "Additionally, leptin has also been implicated in the epithelial-to-mesenchymal transition (EMT) and gain of cancer stemness via the activation of the TGF-b, NOTCH, Hedgehog, and Wnt pathways." (PMID 40558305, 2025). "Moreover, the relationship between sleep disturbances and cancer progression is further explained through the lens of various hormones such as growth hormones, prolactin, dopamine, estrogen, leptin, and ghrelin." (PMID 39980544, 2025). "Additionally, some investigations found similar leptin concentrations between cancer and control groups." (PMID 38534454, 2024). "In vivo, corneal vascularization was observed in WT but not in Ob-R deficient rats, substantiating the notion that an increased leptin expression could enable cancer cells to grow blood vessels." (PMID 39596205, 2024).
cancer (continued). "Furthermore, the hormone leptin, released by adipocytes, promotes cancer stem cell renewal and chemoresistance 46,47." (PMID 38370376, 2024). "Moreover, the adipocyte-derived interleukin-6 (IL-6) and leptin regulate epithelial-mesenchymal transition (EMT) in cancer cells and supports stem cell renewal and chemoresistance 43-47." (PMID 38370376, 2024). "Consequently, leptin acts on its receptors located on various cancer cells, which stimulates the overproduction of MMPs and subsequently enhances cancer cell invasion and progression." (PMID 39518143, 2024). "First, leptin mediates the bidirectional interaction between cancer cells and TAMs." (PMID 39192979, 2024). "Leptin promotes cancer growth while hindering AD development, whereas adiponectin can inhibit cancer progression but may advance AD." (PMID 38534454, 2024). "In addition to its role in remodeling the TME and promoting cancer invasiveness, leptin functions as a growth factor for numerous cancer types." (PMID 39518143, 2024). "Low leptin levels in cachectic patients may also result from the secretion of the leptin-suppressing substance in advanced cancer." (PMID 39337308, 2024). "Leptin levels among cancer patients can vary depending on canctypes and locations." (PMID 38534454, 2024). "Relatively high leptin expression has been found in many cancers." (PMID 39201370, 2024). "Moreover, leptin stimulates cancer cell migration, invasion, CAF induction, and CAF-mediated tumor progression, and changes in the polarity of tumor cells." (PMID 38238841, 2024). "Leptin has a dual effect on cancer progression, its antitumor immunomodulatory effects and mechanisms remain unclear." (PMID 38405061, 2024). "In general, adiponectin inhibits cancer cell growth and leptin promotes cancer cell growth." (PMID 39201655, 2024). "The presence of leptin also stimulates leptin receptor expression in cancer cells." (PMID 38238841, 2024). "Leptin is vastly responsible for DNA damage-induced cancers." (PMID 39692821, 2024). "In addition to promoting tumor cell proliferation, leptin signaling activation upregulates cancer cell production and secretion of soluble VEGFA via NFκB, Sp1, and HIF-1α signaling to induce angiogenic sprouting into the growing tumor mass." (PMID 39439572, 2024). "Leptin and adiponectin secreted by adipocytes are crucial in development of cancer." (PMID 38405061, 2024). "In addition, the role of adipokines, such as leptin and adiponectin, in modulating inflammatory responses and influencing cancer progression has gained attention." (PMID 39335133, 2024). "Leptin activation induces PCa cancer proliferation, promote invasion, and inhibit apoptosis." (PMID 38164282, 2024). "This may be due to several effects of altered leptin signaling, including increased cancer cell resistance to anti-estrogenic drugs (e.g., Tamoxifen)." (PMID 39439572, 2024). "Wnt signaling can be increased by leptin, which promotes cancer cell growth." (PMID 38534454, 2024). "Studies show associations between increased leptin serum levels and increased tumor growth, whereas adiponectin exhibits an inverse and negative correlation with cancer development." (PMID 37686525, 2023). "The reduction in oestrogen-sensitive cancers is consistent with other systematic reviews and is most likely related to the reduction in aromatase activity, plasma and tissue oestrogen and serum leptin and insulin following bariatric surgery." (PMID 37047163, 2023). "Furthermore, leptin can also influence angiogenesis, stimulating the formation of new blood vessels, increasing their permeability, and facilitating the movement of cancer cells through them." (PMID 37238961, 2023). "Furthermore, leptin has been shown to induce telomerase activity in cancer, promoting cell proliferation, and expressing survival factors, leading to chemotherapeutic resistance." (PMID 38068717, 2023). "The relationship between LEP and cancer progression, has been widely explored." (PMID 36941557, 2023).
cancer (continued). "In addition, a significant correlation was observed between serum leptin concentration and cancer staging based on TNM classification (p = 0.021)." (PMID 36981858, 2023). "Leptin can also promote changes in the inflammatory environment by increasing the expression and secretion of different cytokines, which leads to increased migration and invasion of cancer cells in different organs." (PMID 36674935, 2023). "Altered microRNA secretion in adipose tissue may be implicated in oncogenesis, e.g., the exposure of prostate cancer cells to leptin downregulated the expression of micro-RNA-628 and led to increased cancer cell proliferation." (PMID 37048738, 2023). "Moreover, a different team that examined the association of multiple adipokine levels in different cancer types underscored that ER+ cancer patients had significantly higher leptin levels than ER- cases." (PMID 36900364, 2023). "These peptide hormones have antagonistic actions regarding carcinogenesis: leptin may act as a growth factor and promotes an inflammatory environment, while adiponectin suppresses cancer cell proliferation and decreases proinflammatory mediators." (PMID 37364149, 2023). "Moreover, it has been shown that in Ishikawa cells, leptin is able to induce cancer cell growth in a time- and dose-dependent manner." (PMID 37509120, 2023). "This review demonstrates that changing levels of leptin and adiponectin have a significant impact on the incidence, progression and reoccurrence of many cancers; therefore, a correct proportion and relationship between them, which describes the ratio of leptin to adiponectin, are crucial." (PMID 37686525, 2023). "Since adipogenesis underlies obesity and consequent adipocytokine secretion, and several adipocytokines are cancer-promoting (e.g., leptin), KLF9 and KLF13 may significantly affect cancer pre-disposition indirectly through their targeted actions on fat depots." (PMID 38067370, 2023). "Metformin may exert anti-cancer activity by decreasing the circulating estradiol, leptin, and insulin." (PMID 36562831, 2023). "Moreover, we found that knockdown of p73γ or Leptin was able to inhibit growth of E11-KO xenograft tumors, which would open a new revenue for cancer management by targeting the p73γ-Leptin pathway." (PMID 37650871, 2023). "Studies have also suggested that the overproduction of leptin, a hormone-like cytokine synthesized by adipocytes, in the context of MetS may be another important promotor for the invasion and metastasis of malignant tumours." (PMID 37328825, 2023). "On the other hand, it has also been suggested that leptin may stimulate angiogenesis, increase matrix metalloproteinase-2 expression, and lead to cancer metastasis." (PMID 38260162, 2023). "Moreover, different studies have found that leptin circulating levels and leptin receptors are overexpressed in multiple types of cancer, resulting in a poor prognostic significance value." (PMID 37509120, 2023). "Interestingly, calorie restriction is related to delayed PDAC progression and results in increased serum adiponectin and decreased initially deregulated serum leptin in cancer." (PMID 37444627, 2023). "Furthermore, leptin promotes cancerogenesis in many processes, including proliferation, cell survival, and angiogenesis, with consequent cancer progression." (PMID 37190276, 2023). "Interestingly, the same authors showed an increased cancer cell invasion after treatment with leptin at a dose of 100 ng/mL." (PMID 37509120, 2023). "It has been proven that leptin functions similarly to a neoplastic process supporter in cancer." (PMID 37190276, 2023). "Taking into account the fact that leptin activates autophagy in cancer cells, it can also be concluded that an increased level of leptin in the adipose tissue of obese people may contribute to the increased risk of cancer." (PMID 37998742, 2023).
cancer (continued). "Indeed, as with numerous other cancer types, leptin levels are higher in patients with MM compared to controls, supporting the concept of a leptin‐generated pro‐tumour environment." (PMID 37067783, 2023). "The involvement of leptin and adiponectin with receptors in the formation of many types of cancer as well as their impact on the clinical course of cancer patients are well established; however, the mechanisms of action of these adipokines are difficult to understand and thus need to be clarified." (PMID 37686525, 2023). "Leptin induces the proliferation of breast, colon, and gastric cancer cells." (PMID 37942199, 2023). "Indeed, leptin and the leptin receptor are usually overexpressed in cancer patients, wherein this adipokine stimulates proliferation, migratory and invasive potential, and stemness capabilities in the multiple types of tumors here discussed." (PMID 37509120, 2023). "Furthermore, the phenomenon of increased expression of leptin and its receptor has been observed in numerous types of cancers, including TCs." (PMID 37763777, 2023). "In addition, CAAs-induced TGF-β, secreted IL-8, and produced leptin can mediate EMT in cancer cells, promote tumor spread and tumor angiogenesis, respectively." (PMID 37666813, 2023). "We show fasting’s ability to increase CBIs’ antitumour effects to depend on the reduction in circulating insulin, insulin-like growth factor-1 and leptin, which blunts the expression of enzymes from the cholesterol biosynthesis pathway and enhances cholesterol efflux from cancer cells." (PMID 37907500, 2023). "In addition, leptin holds the potential to influence anti-cancer therapy by promoting the proliferation of cancer stem cells." (PMID 38001753, 2023). "Therefore, leptin and adiponectin dysfunction play a prominent role in cancer and impact tumor invasion and metastasis in different ways." (PMID 37686525, 2023). "Collectively, our study reveals a dynamic interaction between cancer and host at the systemic level, and highlights the potential application of targeting both miR-204-5p and leptin signalling pathways in preventive screenings and early intervention for BC cachexia patients." (PMID 37620316, 2023). "To examine whether the effect of circulating miR-204 on thermogenesis and lipolysis-mediated leptin signalling pathway, we employed the db/db mice lack leptin receptor to examine the effect of cancer-derived miR-204 on thermogenesis and lipolysis in WAT." (PMID 37620316, 2023). "For example, leptin mediates immune suppression facilitating cancer formation and progression." (PMID 36831637, 2023). "Additionally, although leptin is mainly secreted by adipocytes, it can also be expressed by pathologically altered cells, such as cancer cells." (PMID 37626804, 2023). "Our study indicates that the p73γ-Leptin pathway promotes tumorigenesis and alters lipid metabolism, which may be targeted for cancer management." (PMID 37650871, 2023). "Consequently, it has been reported that the higher rate of S-phase progression, along with cancer cell proliferation and migration, was evidenced to a greater extent in Type 2 endometrial cancer treated with leptin compared to type 1." (PMID 37509120, 2023). "Leptin concentrations and/or the expression of ObRs in tumors could be used as potential tumor markers in the diagnosis and prognosis of cancer." (PMID 37686525, 2023). "In addition to adipocytes, Leptin was found to be expressed in normal epithelial and carcinoma cells and subsequently promotes tumor growth through autocrine and paracrine signaling." (PMID 37650871, 2023). "Leptin causes higher secretion level in VEGF/VEGFR2 and LIF in carcinoma than benign cells." (PMID 37600567, 2023). "Elevated levels of leptin and its receptors may potentially contribute to the progression of cancer." (PMID 35628118, 2022).